MTOR (mechanistic target of rapamycin kinase)
Diseases named in the same sentence as MTOR in open-access papers (continued):
Sharing a sentence is not in itself a finding about the gene and the disease.
Insulin resistance (continued). "It was recently reported that the STZ/HFD-induced insulin resistance significantly suppresses p-AMPK, p-Pi3k, p-AKT, p-PDK, and p-mTOR axis levels in HepG2 cells, demonstrating that miRNAs play a role in heart illness as fundamental regulators of gene expression." (PMID 36297290, 2022). "Interestingly, we demonstrated that naringin can reduced insulin resistance and increase the mRNA expressions of SOD1, CAT, mTOR, and PGC-1α, while showing significantly decreased expressions of Atrogin-1 and MuRF-1 mRNA." (PMID 36235772, 2022). "Moreover, the activation of RAAS can lead to mitochondrial dysfunction and oxidative stress, which subsequently activates the mTOR/S6K1 signal and perpetuates insulin resistance." (PMID 35454166, 2022). "This may be because prolonged hyperinsulinemia activates the mTOR/S6 kinase pathway, which enhances the serine phosphorylation of IRS-1 and eventually induces insulin resistance in the hypothalamus." (PMID 36353235, 2022). "Moreover, mTOR hyper-activation is also among the known feedback mechanisms promoting IRS1 inhibition and insulin resistance development in AD." (PMID 35628384, 2022). "Furthermore, insulin resistance was improved and the phosphorylation of hypothalamic PI3K/Akt/mTOR proteins involved in insulin signaling was up-regulated." (PMID 36246070, 2022). "The effect of the miR-122-5p inhibitor on NAFLD did not depend on insulin resistance-mediated PI3K/AKT/mammalian target of rapamycin (mTOR) signaling pathway but rather on the upregulation of its downstream FOXO3." (PMID 35222075, 2022). "Naringin not only had improved insulin resistance and increased the gene expression of the antioxidant enzymes (SOD1 and CAT), mTOR, and PGC-1α, but the expressions of IRS-1 and GLUT4 proteins were also increased, which led to increases in the glucose uptake and the glycogen levels." (PMID 36235772, 2022). "Rapamycin and rapamycin analogs have been widely used as immunosuppressants for preventing transplant rejection, but the non-selective inhibition of mTOR activity reportedly impairs glucose homeostasis and increases insulin resistance." (PMID 33670988, 2021). "Overall, the present investigation demonstrates that calystegines from Hyoscyamus albus provide cytoprotection to the HepG2 cells against insulin/glucose induced insulin resistance and apoptosis due to the regulation of SIRT1/Foxo1/G6PC/mTOR and NF-κB/JNK/TLR4 signaling pathways." (PMID 34034759, 2021). "The Janus kinase (JAK)/STAT3 pathway as well as the activation of STAT3 through AKT kinase and mTOR are the important insulin/IGF-1-stimulated, STAT3-mediated signaling pathways which are able to control immunosuppression, immunosenescence, and insulin resistance." (PMID 34476533, 2021). "We implemented a combined bioinformatics analysis to retrieve a set of ceRNA networks (LncRNA-RP11-773H22.4, miR-1, miRNA-3163, which is related to insulin resistance and their targeting signaling pathway genes RET, IGF1R, GLUT4, AKT2 and mTOR mRNAs) from public databases." (PMID 34360895, 2021). "Increased activation of muscle mTOR by nutrient overload or exposure to high insulin leads to increased serine phosphorylation of IRS-1, impaired insulin signaling and induction of insulin resistance." (PMID 32230718, 2020). "We recently demonstrated that Ras homolog enriched in brain is a GTP-binding protein (Rheb), an upstream activator of the mechanistic target of rapamycin (mTOR), serves as a key negative regulator of beige fat thermogenesis, and plays a role in high-fat diet (HFD)-induced insulin resistance." (PMID 31220300, 2019). "Chronic activation of the mTOR/S6K1 pathway by insulin, TNF-α and amino acids promote insulin resistance in obese mice and primary cultures of skeletal muscle cells from patients with type 2 diabetes through increased IRS1 serine phosphorylation and degradation." (PMID 31130916, 2019).
Insulin resistance (continued). "Moreover, mTOR is an important factor in the occurrence and development of NAFLD, as it is involved in the induction of insulin resistance and chronic hepatitis." (PMID 29743930, 2018). "Given the metabolic consequences of NAFLD (i.e. obesity, insulin resistance and T2DM), mTOR involvement is essential in light of its role in cardiovascular diseases such as atherosclerosis, coronary heart disease and stroke (Tarantino & Capone 2013, Patil & Sood 2017)." (PMID 29666152, 2018). "The drug reduces insulin resistance and blood glucose levels through inhibition of mitochondrial respiratory chain complex 1 leading to reduced ATP production and subsequently provoking AMPK activation and mTOR inhibition." (PMID 29866066, 2018). "The results revealed that sitagliptin could attenuate obesity-induced hepatic insulin resistance and steatosis, suppress inflammation by regulating macrophage M1/M2 polarization imbalance, and promote liver autophagy via AMPK/mTOR signaling pathway." (PMID 30123267, 2018). "However, increased glucose and glucosamine uptake bolsters cytosolic ATP production and triggers deviations in cellular behavior, such as insulin resistance, while repressing AMPK and allowing the mTOR pathway to encourage proliferation." (PMID 30237786, 2018). "To investigate whether galangin can get insulin resistance better, we examined the phosphorylation state of ten proteins on the Akt/mTOR signal pathway, including IR, IRS1, PTEN, Akt, GSK3α, GSK3β, TSC2, mTOR, p70S6K, and RPS6." (PMID 30420897, 2018). "Insulin resistance in these pathological conditions results from reduced Akt activation mainly due to inhibition of IRS1/2, likely due to the increased activity of the mammalian target of rapamycin (mTOR) resulting from lower activity of adenosine monophosphate kinase." (PMID 29104874, 2017). "Another study showed that 6 weeks exercise improved skeletal muscle insulin resistance without reduced mTOR/S6K1 signaling pathway." (PMID 27508151, 2016). "There is no doubt that exposure to excess insulin can cause global insulin resistance through a feedback loop that includes tyrosine-phosphorylated IRS1/2, PI3K, Akt, mTOR, S6K, and serine-phosphorylated IRS1/2." (PMID 24741073, 2014). "In aortic endothelial cells, ANG II can stimulate mTOR and p70S6K activation that phosphorylates IRS1 and inhibits endothelial nitric oxide synthase that not only may contribute to insulin resistance but also to vasoconstriction and hypertension." (PMID 22545721, 2012). "Further experimentation perhaps employing other methods of analysis or approaches is necessary to better understand how changes in the basal phosphorylation of p70S6k, mTOR, Akt, and GSK-3β may contribute to pathophysiology of insulin resistance." (PMID 20368999, 2009). "As p70S6k, mTOR, Akt, GSK-3β, and PTEN are thought to be regulated by phosphorylation; it was of interest to determine if the basal phosphorylation status of these proteins is altered with insulin resistance." (PMID 20368999, 2009). "Similarly, the basal level phosphorylation of mTOR (Ser 2448), Akt (Ser 308), GSK-3β (Ser 9), and PTEN (Ser 380/Thr 382/383) was 63.0%, 25.1%, 17.5% and 31.4% higher, respectively, with insulin resistance (P < .05)." (PMID 20368999, 2009). "Insulin resistance may influence cardiac cell metabolism and growth by modulating signaling pathways such as AMPK (AMP-activated protein kinase) and mTOR (mammalian target of rapamycin), thereby affecting the contraction and relaxation functions of the heart during the heart failure process." (PMID 40442740, 2025). "Moreover, elevated ROS levels may activate serine/threonine kinases (e.g., PKC, AKT, mTOR, GSK-3, p38 MAPK), promoting serine phosphorylation of IRS proteins and impairing insulin signaling, thereby facilitating insulin resistance." (PMID 40453670, 2025).
Insulin resistance (continued). "Insulin resistance and hyperinsulinemia accompanied by NAFLD may be involved in liver tumorigenesis by activating intracellular signaling pathways, such as the PI3K/Akt/mTOR pathway." (PMID 39470380, 2024). "Some of the negative effects of mTOR pathway inhibition, such as insulin resistance and hyperlipidaemia, are attributed to the mTORC2 branch of the pathway and may arise under certain conditions of prolonged and/or high-dose rapamycin treatment." (PMID 38956711, 2024). "Insulin induces insulin resistance in human DPSCs and effectively promotes their proliferation, osteogenic differentiation and bone formation capability through gradually inducing the down-regulation of IIS/PI3K/AKT/mTOR pathway axis under insulin resistant states." (PMID 39075596, 2024). "We assessed the gene expression of proinflammatory cytokines, such as IL-1β, IL-6 and TNF-α, as well as mTOR and IKKβ in the adipose tissues of the control and experimental rats in order to assess the ability of C. papaya to mitigate HFD-streptozotocin-incited inflammation and insulin resistance." (PMID 36826001, 2023). "In contrast to these effects, our findings demonstrated that the activation of mTOR/S6K signaling by ER stress in skeletal muscle resulted in a decrease in CRTC2 levels, leading to a subsequent reduction in PGC-1α expression, thereby contributing to the development of insulin resistance." (PMID 35428325, 2022). "Similarly, reduced insulin activity or insulin resistance could result in impaired PI3K/AKT signaling, which controls downstream factors such as mTOR and/or GSK-3β." (PMID 36671395, 2022). "In addition, it has been suggested that insulin resistance in pregnant women with GDM and their newborns may be due to decreased signals of protein kinase B/Akt (Akt) and mammalian target of rapamycin (mTOR) in human placental endothelial cells." (PMID 35720179, 2022). "However, we found no attenuation of mTOR activity in tissues other than the gut, nor an insulin resistance phenotype in mice treated intrarectally with rapamycin." (PMID 35440795, 2022). "As previously discussed, insulin resistance is a common hallmark of T2DM and AD, and it is mainly driven by the PI3K/Akt/mTOR signaling pathway; more precisely, neuronal insulin resistance driven mTOR hyperactivity inhibits IRS1 activity by negative feedback." (PMID 34069890, 2021). "It has been defined that brain insulin resistance occurs primarily with early hyperactivation of insulin signaling, including mTOR hyperactivity, which causes negative feedback on the insulin receptor, IRS1 and mTOR itself." (PMID 34065168, 2021). "Furthermore, a downstream mediator of AKT, mTOR, is more active in insulin resistance macrophages, as demonstrated by significantly greater phosphorylation of mTOR in HFD TEPMs compared to isolated TEPMs from mice fed a normal chow diet for 7 days." (PMID 33100956, 2020). "However, with continuous activation of mTOR, it has a negative feedback loop from p70S6K signaling, contributing to insulin resistance." (PMID 30621146, 2019). "On the other hand, recent studies have shown that insulin resistance can be regulated by Akt/mTOR pathway activation through a negative-feedback loop, but the mechanisms regulating this signaling through cellular energy are not as well defined as those for growth factors and nutrients." (PMID 30544824, 2018). "Besides AMPK signaling pathway, other signaling pathways seem to be related to insulin resistance, including endoplasmic reticulum (ER) stress, mitogen-activated protein kinase (MAPK), and protein kinases B/mammalian target of rapamycin (Akt/mTOR)." (PMID 30420897, 2018). "To test brain insulin resistance, we measured cortical levels of glucose and insulin and analyzed the expression and activation of the insulin receptor (IR) and its downstream signaling molecules IR scaffold-1 (IRS1), protein kinase B (AKT) and mammalian target of rapamycin (mTOR)." (PMID 26858121, 2016).
Insulin resistance (continued). "We can conclude that with the exception of mTOR activation, molecular changes in liver, vWAT and skeletal muscle are related to fructose-induced insulin resistance, and rather than being directly related to the amount of calories ingested, are produced by fructose itself." (PMID 27194405, 2016). "Thus, the Ames fibroblasts are refractory to IGF-1 stimulated phosphorylation of Ser636/639 which could result in the reduced mTOR/S6K1 signaling, attenuation of protein synthesis and decreased insulin resistance." (PMID 26474286, 2015). "However, such type of insulin resistance in normal cells, due to decreased IR and IGF-R signaling, could be beneficial, because the concomitant decrease in mTOR activity can slow down aging, prolong life span and prevent cancer." (PMID 24970814, 2014). "However, considering the unaltered mTOR activation level and prevention of the HFD-induced insulin resistance by reducing gluconeogenesis, we believe that the effect of changes in protein level is not likely the primary contributor to the changes in insulin sensitivity in this study." (PMID 25055153, 2014). "Therefore, the mTOR-S6K signaling pathway was not the likely mechanism of insulin resistance of this study." (PMID 25055153, 2014). "The insulin signal cascades, which include PKB/Akt through PI3K and mTOR, stimulate S6K1, resulting in a negative feedback, which may cause insulin resistance." (PMID 22761194, 2012). "Moreover, we have recently shown that maintenance of cellular mTOR function by anti-hypertensive drugs improves insulin signaling increasing GLUT 4 expression and prevents micro-vascular rarefaction in spontaneously hypertensive rats with insulin resistance." (PMID 20809949, 2010). "However, the expression levels of p-PI3K, p-Akt, and p-mTOR in the hypothalamus were significantly lower in the NAFLD group when compared with the control group (n=3, P<0.01), indicating that HFD resulted in hypothalamic insulin signaling damage which was related with insulin resistance." (PMID 36246070, 2022). "Therefore, the AKT-independent activation of mTOR by p62 and the resulting increase in skeletal muscle mass might at least in part provide the mechanism by which p62 in muscle ameliorates insulin resistance independent of the AKT-GLUT4 pathway." (PMID 36439272, 2022). "For example, TNF-activated signaling molecules such as IKK, JNK, S6 kinase, and mammalian target of rapamycin (mTOR) could potentially phosphorylate insulin receptor substrate 1 (IRS1) to attenuate insulin signaling and subsequently contribute to the development of insulin resistance." (PMID 33150865, 2020). "As the potential effector molecules involved in insulin resistance, the levels of mTOR, phosphorylated mTOR and downstream phosphorylated S6K were increased in the TNF-α and IL-6-treated groups, suggesting that the mTOR/S6K pathway may be involved in insulin resistance under inflammatory stress." (PMID 26449763, 2015). "In addition, the elevated expression of T-cad was suggested to be involved in the pathogenesis of insulin resistance in endothelial cells through the mechanism of chronic activation of the Akt/mTOR-dependent negative feedback loop and the increased degradation of insulin receptor substrate." (PMID 24136461, 2014). "Indeed, insulin-resistance and compensatory hyperinsulinemia in obese patients may exert proliferative effects on human orbital preadipocytes/fibroblasts via the phosphatidylinositol 3-kinase (PI3-K) and the mammalian target of rapamycin (mTOR) signaling pathways." (PMID 36060941, 2022). "Meanwhile, the activation of mTOR/S6K also enhances the negative feedback signaling to IRS1, resulting in insulin resistance in hepatocytes." (PMID 25334061, 2014). "Overactivation of mTOR/S6K cascade would exert a significant negative effect on the activity of downstream components of the insulin/PI3-K pathway, such as AKT, leading to insulin resistance." (PMID 24151517, 2013).
Insulin resistance (continued). "For example, mTOR is involved in the development of insulin resistance via a negative feedback loop, i.e. the inhibition of IRS-1 tyrosine phosphorylation, while the inhibitory effect of curcumin on mTOR has been demonstrated in certain cancer cells." (PMID 22253696, 2012). "Yet, mTOR may have a negative feedback loop and can inactivate IRS that may lead to poor insulin signaling and insulin resistance in the cardiovascular system." (PMID 22545721, 2012).